IL4 (interleukin 4)
Diseases named in the same sentence as IL4 in open-access papers (continued):
Sharing a sentence is not in itself a finding about the gene and the disease.
asthma (continued). "We also recently reported that the NFAT‐interacting protein (NIP)‐45, which induced IL‐4 by potentiating NFATc2, is induced in preschool children with asthma and NIP45 deficient mice have less airway eosinophilia." (PMID 33079489, 2020). "This was attributed to elevated circulating Th2 and Th17 cells, along with their associated cytokines IL-4 and IL-17A respectively, at both early and advanced stages of pathology in the apoE−/− mice with asthma." (PMID 32194407, 2020). "In particular, besides the downstream effectors of type 2 airway inflammation such as IgE, IL-5, IL-4/13 and their receptors, other very interesting pathogenic molecules include upstream activators of cellular pathways leading to T2-high asthma." (PMID 33329598, 2020). "Asthma is a T helper type 2 (Th2) cell-mediated eosinophilic inflammatory disease, and Th2 cytokines IL-4, IL-5, and IL-13 have been implicated in asthma pathology." (PMID 31852931, 2019). "More importantly, 11 mRNAs were overlapped in our sequencing data, MalaCards database and asthma-associated genes, including IL4, IL-10, MMP9, VCAM-1, Il1rl1, Alox5, Il1rn, Ccr3, Cysltr1, Epx, and Ccl24." (PMID 31231429, 2019). "The absence, or reduced concentration of IL-10, associated with asthma enables the continued secretion of pro-inflammatory cytokines that contribute to lower airway inflammation, including IL-6, IL-5, IL-4, TNF-α, and IL-1." (PMID 31694631, 2019). "Some studies conducted on allergic rhinitis and asthma showed that there is an association of IL-4 with significant increase in TNF-α." (PMID 31871471, 2019). "Aberrant production of the Th2 and Th17 cytokines, IL-4, IL-5, IL-13, and IL-17, mediate the induction of the IgE isotype switch, which has long been associated with the pathogenesis of asthma." (PMID 30873032, 2019). "In the context of asthma associated with Th2 responses, it is possible that recruited NK cells will produce IL-4, IL-5, and IL-13 over IFN-γ, contributing therefore to both the pathology of asthma and impaired antiviral responses." (PMID 31167464, 2019). "Evidence suggests that Th2 cytokines (IL-4, IL-13, and IL-5) play pathogenic roles in allergy and asthma." (PMID 32411263, 2019). "Catalpol (5–10 mg/kg daily i.p.)alleviated inflammation of the airways and histopathological changes in the lungs of mice with ovalbumin-induced asthma; this was associated with the suppression of IL-4, IL-5, IL5Rα, and immunoglobulin E (IgE)." (PMID 31878316, 2019). "Eotaxin-2, which is a major chemoattractant for eosinophils, is highly expressed in allergic inflammatory tissues; it is also a featured eosinophil chemokine, likely to be involved in the IL-4-associated immune responses and allergen-induced asthma." (PMID 30823378, 2019). "In consideration of the important role of pathogenic Treg cells, how IL-4 produced by Treg cells individually can affect the pathogen of asthma needs more experiments." (PMID 30013989, 2018). "TH2 cells mainly secrete the cytokines IL-4, IL-5, and IL-13 to mediate inflammatory and remodeling changes in the airway mucosa that predispose an individual to asthma and to asthma exacerbations." (PMID 29951106, 2018). "Asthma is generally associated with Th2 cells, which produce a panel of cytokines (IL-4, IL-5, IL-13) that act in synergy to drive lung inflammatory responses, mucus secretion, IgE production, and fibrosis, causing the characteristic symptoms of asthma." (PMID 30105031, 2018). "Alterations in the IgE and IL-4 levels are considered key markers of anti-asthmatic effects since the inflammatory response associated with asthma is characterized by infiltration of Th2 cells and leukocytes, and is characterized by elevated IgE in serum." (PMID 30360392, 2018).
asthma (continued). "Group II ILCs specifically, secrete the cytokines IL-5, IL-13, IL-9, amphiregulin, and low quantities of IL-4 and have been linked to several lung-associated conditions including pathogen infections (viruses and helminths), asthma, and pulmonary fibrosis." (PMID 30413212, 2018). "Most patients with asthma have an eosinophilic infiltration of the airways, associated with increased production of type 2 cytokines including IL-4, IL-5, IL-13 secreted by Th2 cells, together with allergic comorbidities." (PMID 30105031, 2018). "Uteroglobin/CC10 deficiency caused asthma-like airway inflammation, together with eosinophil-dominance and high expression of type 2 cytokines, including IL-4 and IL-13." (PMID 29642409, 2018). "In mouse models of asthma induced by diisocyanates, a group of known chemical asthmogens, it has been shown that both Th2 and Th1 cytokines, including IL-13, IL-4 and IFN-γ, are associated with the development of asthma features." (PMID 28704401, 2017). "By doing so, we were able to replicate the importance of the IL4 CpG−48, previously shown and validated as associated with urban asthma." (PMID 28588744, 2017). "Mixed responses characterized by IL-5 and IL-17 upregulation were associated with Difficult-to-Control disease while IL-4 and IL-13 were associated with Easy-to-Control asthma." (PMID 28686637, 2017). "The association of P and asthma (P + A) decreased (p<0.001) the production of IL-4 in relation to the (Asthma) group." (PMID 29145431, 2017). "CXCL-1, IL-5, IL-8, and IL-17A were positively associated with Difficult-to-Control asthma, while IL-4 and IL-13 were positively associated with Easy-to-Control asthma." (PMID 28686637, 2017). "Several IL-4 -590C/T polymorphism studies were reported in various autoimmune diseases, including asthma, rheumatoid arthritis, and multiple sclerosis." (PMID 28511637, 2017). "Human asthma is associated with increased basal IL-4 and IL-13 levels in the airway, and segmental airway challenge with allergen induced IL-4 and IL-13 responses." (PMID 29182669, 2017). "IL-4 signaling, which is associated with allergy and asthma through development of T-cell-mediated immune responses, was significantly enriched among downregulated genes." (PMID 26976439, 2016). "Th2 cells produce high level of IL-4, IL-5 and IL-13 which are closely associated with asthma symptoms." (PMID 27870920, 2016). "Asthma is a prevalent disease of chronic inflammation in which the Th2 cytokines IL-4, IL-5, and IL-13 are all tightly linked to the pathogenesis of asthma." (PMID 27547445, 2016). "More specifically, Tbet deficient T cells have been shown to drive airway IL-4 production and hyperreactivity in an asthma model and both IL-13 and IL-17A have been shown to be able to drive allergic airways disease in Tbet deficient mice." (PMID 27683080, 2016). "Th2-type cytokines (such as IL-4, IL-5, and IL-13) and chemokine (eotaxin) have been implicated in the promotion of allergic responses in asthma." (PMID 27741312, 2016). "Nevertheless as described, this model demonstrates the hallmarks of airway inflammation associated with human asthma, employing the critical processes driven by both the cytokines IL-4 and IL-13." (PMID 26740570, 2016). "Th2 cells are the central players in allergic asthma, as they are major producers of the type 2 cytokines interleukin-4 (IL-4), IL-5, and IL-13, which are all tightly linked to the pathogenesis of asthma." (PMID 26965110, 2016). "In pathway analysis, these transcripts were enriched for Th2 associated responses exemplified by genes linked to asthma and IL4-mediated signalling events." (PMID 26986567, 2016). "Alternatively, RV-associated asthma exacerbations are linked to increased expression of a type 2 cytokine signature (IL-4, -5, and -13) suggesting an alternative (or complementary role) for aberrant adaptive immune responses." (PMID 25584821, 2015).
asthma (continued). "IL-4 is the primary cytokine implicated in the development of Th2-mediated responses, which is associated with allergy and asthma." (PMID 25982058, 2015). "Arginine at this position is associated with altered IL4 signaling, a shift of the Th1/Th2 balance toward Th2, and susceptibility to asthma and several connective tissue disorders, including systemic lupus and scleroderma." (PMID 26540410, 2015). "Th2-type cytokines IL-4, IL-5, and IL-13 have been implicated in promoting allergic responses in asthma." (PMID 26110056, 2015). "The CT/TT-genotype of IL4 rs2070874 (p = 0.07) and the CT/TT-genotype of rs2243250 (p = 0.06) were positively associated with childhood asthma." (PMID 25768087, 2015). "Polymorphisms in ADAM33, ORMDL3/GSDMB and IL4 were associated with childhood asthma in a group of children with recurrent wheeze." (PMID 25768087, 2015). "Polymorphisms in ADAM33 (rs511898 and rs528557) and ORMDL3/GSDMB (rs7216389) were negatively associated and polymorphisms in IL4 (rs2070874 and rs2243250) were positively associated with childhood asthma." (PMID 25768087, 2015). "The IL-4 gene polymorphism and susceptibility of various diseases like asthma and malaria were studied in Caucasian population, but susceptibility of sepsis in trauma patients was showed by limited number of studies." (PMID 26561011, 2015). "IL-13 as IL-4 are more involved in allergic inflammation and are increase in experimental model of asthma and IL-13 is strongly associated to mucus production be epithelial cells." (PMID 25816137, 2015). "SNP IL4-590 C/T has been repeatedly associated to asthma in several population backgrounds and the results of this study in the Madeira island population are no exception (previously reported by our research team." (PMID 25299150, 2014). "Among the Th2 cytokines, IL-4 and IL-13 are investigated the therapeutic intervention in asthma and other Th2-associated diseases." (PMID 24936861, 2014). "In fact, every haplotype found to associate with the risk of asthma includes either IL4-590 C/T or IL4-RP2183/253 or both." (PMID 25299150, 2014). "This SNP has been implicated in childhood asthma in a Chinese population, where authors suggest a link between the allele and higher expression of IL4 in asthma." (PMID 25299150, 2014). "IL-4 and IL-13 orchestrate asthma-associated inflammation and are Th2 cytokines that are produced not only by lymphocytes but also by mast cells, eosinophils and macrophages." (PMID 24040386, 2013). "Numerous other genes have been associated with asthma and related phenotypes, including those related to T helper cell (Th) pathways (IL-4, IL-13, IL-4Rα, TNFα and LTΑ)." (PMID 23573270, 2013). "A recent study showed that the excessive production of interleukin (IL)-4, IL-5, and IL-13 by T-helper type 2 (Th2) cells is implicated in the development of asthma." (PMID 22203879, 2012). "The human variant of the 15-LOX enzyme in monocytes and alveolar macrophages can be induced by interleukins associated with asthma, including IL-4 and IL-13." (PMID 21897859, 2011). "One of the variants (rs2243250), which was most strongly associated with asthma, lies in the IL4 promoter region which has been implicated and replicated in more than 11 studies." (PMID 21387019, 2011). "In the case of IL4 gene polymorphism, C-590T (rs2243250), locating in the promoter region, has been shown to be associated with asthma." (PMID 22087298, 2011). "Considering the number of assays performed, IL4 showed an excess number of significant SNPs associated with asthma (4 out of 5), while a larger gene such as CLCA1, with 23 SNPs, showed no significant SNP associations." (PMID 21387019, 2011). "The IL-4, IL-13, and IL-4Rα interaction pathway have been implicated in the pathogenesis of AR and asthma." (PMID 22087298, 2011).
asthma (continued). "The chromosome 5q31 locus which has been linked to blood P. falciparum parasites density also contains the genes encoding the cytokines IL-4, IL-5, and IL-13, and these have been associated with inflammatory diseases including asthma." (PMID 22216286, 2011). "With this criterion, 4 SNPs in IL4 significantly increased the risk for asthma by approximately twofold." (PMID 21387019, 2011). "First, we confirmed the importance of IL4 genetic variation in the risk of pediatric asthma, and present evidence of replication among the African-American population." (PMID 21387019, 2011). "We identified IL4 as having a role in asthma susceptibility in both African American and Caucasian children." (PMID 21387019, 2011). "Genes within the chromosome 5q cytokine cluster have demonstrated strong associations with asthma/allergy, most notably for IL4 and IL13." (PMID 21320344, 2011). "At the top of the tree, the most asthma predictive SNP was rs2243250, an extensively studied IL4 promoter variant." (PMID 21387019, 2011). "In asthma we found a positive association of IL-4 with IL-5, and significant association with IL-13, TNF α as well as GM-CSF, while IL-5 is positively associated with IL-4, IL-10 and GM-CSF." (PMID 20616938, 2010). "Further SNPs in DPP10, IL12B and IL4 were now found to be associated with asthma in our population, but only at the nominal significance level of 0.05." (PMID 21103062, 2010). "We found that there is a strong association of IL-4 cytokines with IL-5 in most of cases of allergic rhinitis, asthma, urticaria as well in patients showing skin and rhinitis." (PMID 20616938, 2010). "Human chromosome 5 has also been implicated to contribute to asthma as both IgE and IL-4 are found on 5q31.1." (PMID 20497568, 2010). "If the resultant inflammatory response is T helper-2 dominant, cytokine mediators typically associated with asthma [interleukin (IL)-4, IL-5, IL-9, IL-13] would subsequently be produced." (PMID 20064771, 2010). "The most prevalent gene symbol in the retrieved abstracts for genetic association with asthma was IL4 (91 citations) followed by IL13 (75 citations) and TNF (73 citations)." (PMID 21103062, 2010). "IL-4 gene is located on chromosome 5q31, it was suggested to be associated with asthma risk, including elevated serum IgE levels and airway hypersensitiveness." (PMID 20868478, 2010). "Based on findings in a murine model of maternal transmission of asthma risk, we sought to test the role of the pro-asthmatic cytokines interleukin IL-4 and -13." (PMID 19252738, 2009). "Arginase-1 in macrophages is induced by Th2 type cytokines such as IL-4, IL-10, IL-13 and IL-21 and increased arginase is associated with resistance to worm infections, allergic conditions such as asthma and Th2 induced pathologies." (PMID 19696894, 2009). "In summary, PT, CR and their combinational prescription have deep inhibitory effects on airway inflammation in a murine model of asthma and it was caused by suppression of Th2 cytokines (IL-4, IL-5, IL-13), IgE, eosinophil CCR3 expression in lung." (PMID 19657453, 2009). "Toluene diisocyanate treated interleukin-4 deficient mothers were able to transfer asthma risk to offspring." (PMID 17662138, 2007). "Genetic variation in the IL4 gene has shown linkage to atopy and asthma in several studies; common promoter polymorphisms including the IL4(-589C>T) SNP have been associated with asthma and/or atopy in many studies." (PMID 16759385, 2006). "Specifically, the promoter region of IL4 has been associated with asthma phenotype and a -33C>T polymorphism has been reported in this region." (PMID 16313681, 2005). "Evidence that IL4 polymorphisms are associated with total IgE levels and potentially with asthma and other allergy related phenotypes has been provided, although ethnical differences have been reported." (PMID 16313681, 2005).
asthma (continued). "In that sample, nearly all of the haplotypes that were associated with asthma and the one most strongly associated with atopy included the IL4_-589T allele and other SNPs in the IL4 gene (SNP2-T, SNP4-A, IL4_+3017T, IL4_+8374G, SNP8-C)." (PMID 16336695, 2005). "We finally compared the levels of IgE and IL-4, two important known risk factors for asthma, in the 95 asthma patients who were either positive (37 patients) or negative (58 patients) for the presence of anti-Hsp60 and anti-Hsp70." (PMID 15710045, 2005). "Variants in the IL4 gene, including rs2243250 and rs2243248, have been associated with asthma susceptibility and severity in different populations; however, their role in the Mexican population remains unclear." (PMID 42278241, 2026). "Th2 cytokines IL-4 and IL-13 cause AECs dysfunction in asthma." (PMID 41555513, 2026). "Its overexpression was associated with decreased levels of ovalbumin-specific IgE, IL-4, IL-5, and IL-13, contributing to improved asthma outcomes by limiting airway remodeling and autophagy through the downregulation of matrix metalloproteinase (MMP)-16 and autophagy related 7 (ATG7)." (PMID 40871238, 2025). "Additionally, the commonly used drug for treating cough-variant asthma, montelukast sodium, was recently shown to reduce the inflammatory factor IL-4 and increase the anti-inflammatory factor interferon (IFN)-γ, thereby enhancing pulmonary function." (PMID 40722500, 2025). "The increased understanding of such complex inflammatory pathways has resulted in the development of antibody-based biological therapies that target T2 cytokines such as IL-4, IL-5, and IL-13, which play key roles in the inflammatory processes underlying asthma." (PMID 41440490, 2025). "In addition, stress has a stimulating effect on the production of certain cytokines (e.g., interleukin (IL)‐4, IL‐5, IL‐13) associated with asthma." (PMID 40702946, 2025). "Asthma often begins in childhood (childhood-onset asthma) and is often associated with exaggerated type 2 immunity, involving the production of the prototypical type 2 cytokines IL-4, IL-5, and IL-13." (PMID 41145900, 2025). "We did not directly compare HDM exposure between our mixed background mice and C57BL/6 mice, which are generally more prone to neutrophilic inflammation in ovalbumin-induced asthma models, which may underlie the weaker IL-4, IL-5 and IL-13 responses observed." (PMID 41146597, 2025). "These protective effects were linked to changes in CpG methylation at the promoter regions of IFN-γ and IL-4 genes, suggesting that fungal exposure may influence asthma risk through epigenetic reprogramming." (PMID 40806756, 2025). "Consequently, changes in the mRNA expression levels of the five major IL-4/IL-13 pathway genes, which are DNA variants, lead to gene expression changes, which lead to asthma susceptibility and subsequently elevated serum IgE." (PMID 40375219, 2025). "In the PPI network analysis, lililin was found to be associated with three asthma drug targets (IgE, IL-5, and IL-4), further indicating that lililin may be a potential therapeutic target for asthma." (PMID 39806440, 2025). "Type 2 (T2)-high asthma, characterized by eosinophilic inflammation and elevated IL-4, IL-5, and IL-13 pathways, has been associated with a more robust Th2 response, which may mitigate the hyperinflammatory state triggered by SARS-CoV-2 infection." (PMID 41149067, 2025). "Notably, IL-4 has been clinically established as a key mediator associated with asthma susceptibility and disease pathogenesis." (PMID 41035881, 2025). "Moreover, asthma is associated with the occurrence of atopic dermatitis, chronic sinusitis, allergic rhinitis, and a high profile of T2-type cytokines, such as IL-4, IL-5 and IL-13." (PMID 40723867, 2025).